AKR1B10 (aldo-keto reductase family 1 member B10)
Diseases named in the same sentence as AKR1B10 in open-access papers (continued):
Sharing a sentence is not in itself a finding about the gene and the disease.
cancer (continued). "Aldo-keto reductases overexpressed in our cancer dataset (AKR1C1, AKR1B10, and AKR1C3) are involved in the reduction of retinal to retinol." (PMID 25243088, 2014). "Four enzymes (TPI1, AKR1B10, ALDOA, and AKR1B1) out of 34 enzymes in this pathway are overexpressed in cancer." (PMID 25243088, 2014). "However, in certain cancers, ACC evades degradation through interactions with AKR1B10, enhancing FA synthesis and driving tumor progression." (PMID 40370434, 2025). "Additionally, 18 CCC, 5 HGSC and 12 MC HSGs had OncoScore > 50, among these were candidate cancer biomarkers such as RNASET2 for CCC, AKR1B10 for HGSC, and KRT20 for MC." (PMID 40390000, 2025). "Initially, differentially expressed genes related to HCC were identified from the GEO database, and the expression of AKR1B10 in HCC and other cancers was compared using TIMER and GEPIA databases, with validation of its specificity in HCC tissue samples using the HPA database." (PMID 38802416, 2024). "CNV analysis showed that there are no distinct change in AKR1B10 expression among different types of CNV in most cancers." (PMID 39712017, 2024). "Limited by the complexity of the TME, the effect of AKR1B10 on GC cells is not sufficient to explain the important role of this gene in the development and progression of cancers." (PMID 37039038, 2023). "In addition, the LINC00665/miR-98-5p/AKR1B10 axis can activate the MAPK signaling pathway and its downstream gene MMPs, thereby promoting tumor cell invasion and cancer metastasis." (PMID 35563845, 2022). "By contrast, in other tissues with normally low or no expression, the evidence is mounting that AKR1B10 is upregulated and involved in several forms of cancer and inflammatory disease." (PMID 34063865, 2021). "AKR1B10 inhibitors are also targets for drug discovery research in cancer treatments, as AKR1B10 disrupts RAR- and RXR-mediated biological control and is responsible for increased proliferation of cancer cells." (PMID 35052547, 2021). "It has been reported that AKR1B10 is secreted through a lysosome-mediated nonclassical pathway, leading to an increase in the serum of cancer patients." (PMID 32547320, 2020). "It is important to note that some of the genes that we have identified and confirmed by qRT-PCR (such as AKR1B10 and JPH1) may serve as potential candidates for targeted therapeutics in cancer." (PMID 22912720, 2012). "Identification of Akr1b8/AKR1B10 protein domain interacting with ACCA would be helpful to predict this characteristic for other AKR1B proteins and to develop targeted therapeutic strategies for the modulation of de novo fatty acid synthesis in cancer cells." (PMID 22876234, 2012). "We next tested whether AKR1B10 gene expression could also be useful to inform presence of cancer in the absence of exposure to smoking." (PMID 32097409, 2020). "The present work demonstrates that AKR1B10, AKR1C1, AKR1C2 and AKR1C3 are transcriptional targets strongly indicative of NRF2 status in human tumours, and that NRF2 is the upstream effector of AKR overexpression in cancer, particularly in tumours of squamous origin." (PMID 27824809, 2016). "In addition, AKR1B10 may be upregulated by the activation of some signal transduction pathways, such as MAPK, Nrf2, and AP-1 pathways, and promote the proliferation and migration of cancer cells." (PMID 36845547, 2023). "Analysis using the GEPIA database, which combines TCGA and GTEx data, indicated that at the mRNA level, AKR1B10 expression in HCC was higher than in non-cancerous tissues, both in non-paired samples and paired samples, consistent with the pan-cancer analysis results." (PMID 38802416, 2024). "AKR1B10 is known to be secreted via a non-canonical pathway due to its interaction with the HSP90 protein, and could act distantly since it favours metastasis growth in an indirect co-culture cancer model." (PMID 35163833, 2022).
cancer (continued). "In addition, to the best of our knowledge, m6A-related AKR1B10 in cancer has not been reported; therefore, our study provides the first evidence that the tumor-promoting function of METTL3 is dependent on the m6A modification of AKR1B10." (PMID 36476503, 2022).
tumor (101 papers, 2009 to 2026). "Overexpression of AKR1B10 was associated with tumor size, invasion, recurrence, and poor overall survival as well as DFS." (PMID 39055885, 2024). "Their investigation of genes associated with AKR1B10 led to the discovery that the tumor-promoting function of methyltransferase 3 (METTL3) relied on the N6-methyladenosine (m6A) modification of AKR1B10." (PMID 39737179, 2024). "Elevated AKR1B10 expression was significantly associated with gender, primary tumor size, and fibrosis stage in HCC tissues." (PMID 38802416, 2024). "We evaluated the association of AKR1B10 expression with components of tumor microenvironment and clinical outcomes." (PMID 39712017, 2024). "It is important to note that tumors are heterogeneous, and the pathogenic and metabolic mechanisms of AKR1B10 can differ between different tumor types." (PMID 39737179, 2024). "In the current study, we aimed to evaluate the diagnostic value of AKR1B10 in serum and tumor tissue for HCC, its ability to distinguish HCC from benign liver disease, and its accuracy in diagnosing early-stage HCC." (PMID 36584078, 2022). "Consistent with the results of the CCK8 assay, overexpression AKR1B10 significantly promoted tumor growth, while loss of AKR1B10 inhibited tumor growth in vivo." (PMID 34419144, 2021). "Since FGF1 is associated with inflammation in the tumor microenvironment, we next analyzed the potential correlation between AKR1B10 and FGF1 in TCGA datasets." (PMID 32615540, 2020). "AKR1B10 was overexpressed in HCC compared with non-tumor tissue and associated with histological grade, showing much higher levels in well-differentiated HCC compared to moderately differentiated tumor." (PMID 30959792, 2019). "Nevertheless, survival analysis showed that high expression of AKR1B10 was a predictor for low risk of early tumor recurrence in patients with HBV-related HCC after liver resection." (PMID 28181486, 2017). "Multivariate analysis also identified high AKR1B10 expression as an independent predictor for low risk of early tumor recurrence in patients with HBV-related HCC after liver resection." (PMID 28181486, 2017). "The genes of the SLC family such as SLC2A14 and SLC2A3 and the AKR1 (aldo-keto reductase 1) family such as AKR1C1, AKR1C2, AKR1C3 and AKR1B10 were associated with the metabolic processes of tumor cells." (PMID 20003295, 2009). "Furthermore, high levels of AKR1B10 in saliva were associated with larger tumor sizes, more advanced clinical stages, and the habit of chewing areca." (PMID 40723410, 2025). "Detailed mechanism analysis suggests that it may influence the development and prognosis of HCC by regulating the tumor microenvironment through the underlying DANCR-miR-216a-5p-AKR1B10 axis." (PMID 38802416, 2024). "Furthermore, AKR1B10 expression is associated with keratinization and tumor recurrence in cervical cancer." (PMID 39055885, 2024). "Herein, we analyzed the association of AKR1B10 expression with tumor purity." (PMID 39712017, 2024). "Tumor recurrence was associated with AKR1B10 expression after surgery for cervical cancer." (PMID 34063865, 2021). "Interestingly, integrative analysis of TCGA RNAseq data and miRNA-seq data predicted that miR-383-5p, a novel post-transcriptional tumor suppressor, is negatively associated with AKR1B10 expression." (PMID 30038373, 2018). "verified that AKR1B10 was expressed predominantly in the cytoplasm of GC cells and that positive expression of AKR1B10 was associated with lymph node metastasis and poorer tumor response to neoadjuvant chemotherapy, which indicated a poorer prognosis for the patient." (PMID 39737179, 2024). "This further suggested that AKR1B10 may be associated with the tumor progression." (PMID 34419144, 2021). "High AKR1B10 expression could predict low risk of early tumor recurrence." (PMID 28181486, 2017). "Spatial transcriptomics data (HCCDB) also confirmed uniformly higher AKR1B10 expression in tumour regions versus para‐tumour regions." (PMID 41454479, 2026).
tumor (continued). "Samples were categorized into low, medium or high AKR1B10 expression based on immunoreactivity, and AKR1B10 expression was significantly lower in adjacent non‐tumour tissues than in HCC tissues." (PMID 41454479, 2026). "Immunohistochemical analysis of these tumours confirmed that the combination therapy significantly reduced the expression of both AKR1B10 and LDHA." (PMID 41454479, 2026). "Immunohistochemical (IHC) staining of xenografts revealed strong AKR1B10 expression in tumours harbouring wild‐type AKR1B10, indicating that the K173R mutant failed to maintain AKR1B10 protein levels in vivo." (PMID 41454479, 2026). "AKR1B10 exerts a tumor-suppressive effect in CRC by inactivating FGF1 and represents a novel target for combination therapy in CRC68." (PMID 41006647, 2025). "Specifically, ALB and CYP2E1 were highly expressed in normal areas, GPC3 and AKR1B10 were highly expressed in tumor areas, ACTA2 and COL1A1 were highly expressed in fibrostic areas, and PTPRC was highly expressed in inflammation areas." (PMID 40051627, 2025). "In summary, this study uncovers the tumor-suppressive attributes of the aldo-keto reductase AKR1B10 in CRC (phenocopies in GC), where it unleashes PP2A activity through both its redox regulatory capacity and moonlighting, binding-dependent function." (PMID 40845116, 2025). "Our findings reveal a contrasting role for AKR1B10 as a tumor suppressor in CRC metastasis, mediated through posttranslational activation of PP2A." (PMID 40845116, 2025). "In particular, Cyfra 21-1 was correlated with tumor differentiation and recurrence, while AKR1B10 emerged as a significant predictor of poor OS when levels exceeded 646 pg/mL in early-stage OSCC." (PMID 41149126, 2025). "In other words, the OS was significantly lower in cases showing positive tumor expression of AKR1B10." (PMID 40142797, 2025). "Several studies identified proteins such as Cyfra 21-1, Cathepsin B, AKR1B10, IL-10, IL-13, and TNF-α as being associated with tumor burden, histological grade, or recurrence risk." (PMID 41149126, 2025). "In AML, tumor expressions of AKR1B10, which degrades idarubicin, and AKR1B1, which inhibits the metabolism of idarubicin are important prognostic factors." (PMID 40142797, 2025). "Further, they found that the knockdown of AKR1B10 reversed the tumor-promoting effects induced by METTL3 overexpression." (PMID 39737179, 2024). "A recent study showed that AKR1B10 led to the increase of immunosuppressive signals in the tumor microenvironment by influencing the polarization of M2-type macrophages, providing favorable conditions for the development of gastric cancer." (PMID 38802416, 2024). "In tumor microenvironment, AKR1B10 was significantly correlated with immune cell infiltrations and immune gene expression." (PMID 39712017, 2024). "Given the multifunctionality of AKR1B10 in metabolism and tumor biology, exploring its expression pattern and function in more GI tumors will be a promising research direction." (PMID 39737179, 2024). "To explore the correlation between AKR1B10 expression and tumor immune response, we used the TIMER database for further analysis." (PMID 38802416, 2024). "Results exhibited that AKR1B10 protein was undetectable in 374 (63.13%), weakly positive in 146 (24.66%), and positive 72 (12.16%) of 592 tumor tissues." (PMID 38370384, 2024). "It has been confirmed that AKR1B10 exerts a regulatory influence on EMT, which is inversely linked to with tumor volume, infiltration depth, and metastasis." (PMID 39737179, 2024). "The differential expression of AKR1B10 in tumor and normal tissues has prompted the exploration of its role in tumor therapy." (PMID 39737179, 2024).
tumor (continued). "The study of AKR1B10 and its relationship with digestive system tumors has revealed its potential role in regulating the proliferation and migration of tumor cells through involvement in the PI3K/AKT and Kras signaling pathways." (PMID 39737179, 2024). "While AKR1B10 expression was significantly higher in HCC tumor tissues relative to normal tissues, AKR1B1 expression was not remarkably different between tumor and normal tissues." (PMID 39055885, 2024). "As a carcinogenic protein, AKR1B10 promotes tumor occurrence and development by enhancing fat production and is involved in pancreatic carcinogenesis via modulating the Kras-E-cadherin pathway." (PMID 36714025, 2023). "We noted a dramatically high mean H score for ACSL4 and AKR1B10 in tumors compared to normal liver (mean tumor H score minus mean normal H score were 105.5 and 185.0 respectively)." (PMID 36829466, 2023). "It is worth mentioning that the effect of AKR1B10 on tumor metabolic reprogramming displays significant heterogeneity." (PMID 37587486, 2023). "A differential abundance analysis between proteomes of NK cells isolated from liver and tumor tissues identified four proteins that were increased in tumor NK cells (Log2 fold change > 2; p value < 0.01): AKR1B10, GLUL, IGHMBP2, and AFAP1L2." (PMID 37388918, 2023). "The level of mRNA for AKR1B10 (reduces all-trans retinaldehyde to retinol) was increased within 80% of tumor samples." (PMID 37569466, 2023). "AKR1B10 encodes a member of the aldo–keto reductase (AKR) 1B subfamily and exerts variable or even opposing roles in different tumor contexts." (PMID 36829161, 2023). "Silencing of AKR1B10 in these tumor cells downregulated MMP2 and MMP9 expression, suppressing both in vitro and in vivo tumor cell extravasation across the BBB." (PMID 37688612, 2023). "We have used this chip to demonstrate that AKR1B10 is promotive for tumour cell extravasation through the BBB." (PMID 37830128, 2023). "5&6) AKR1C3 and AKR1B10 are enzymes that catalyzes redox transformation and play important role in tumor progression." (PMID 36959981, 2023). "It is noteworthy that in these cohorts, the expression of AKR1B10 evaluated by RT-PCR and Western blot was in a relatively low number of tumor tissues compared to the previous reported." (PMID 35280770, 2022). "Our meta-analysis indicated that AKR1B10 as a tumor marker has the ability to distinguish HCC from benign liver disease." (PMID 36584078, 2022). "In this study, we demonstrated that AKR1B10 exhibits a similar expression pattern and tumor-promoting effects in CCA." (PMID 36476503, 2022). "Enzyme linked immunosorbent assay (ELISA), Time-resolved fluoroimmunoassay (TRFIA), Reverse transcription polymerase chain reaction (PT-PCR) and Immunohistochemistry was used to determine the expression level of AKR1B10 in serum and tumor tissue." (PMID 36584078, 2022). "AKR1B10 protein functions as an oncogenic protein that promotes tumor development and progression through elimination of cytotoxic carbonyl compounds and elevation of lipogenesis." (PMID 35280770, 2022). "One piece of work in our study has demonstrated that miR‐383‐5p suppresses tumor growth through directly binding to and degrading AKR1B10 mRNA." (PMID 35924788, 2022). "AKR1B10P1, an isoform pseudogene of oncogenic AKR1B10, is validated as a down-stream target degraded by tumor-suppressing miR-138, and there existed a positive feedback from AKR1B10P1, by which miR-138 interacts with AKR1B10P1 via a ceRNA approach in HCC." (PMID 36028503, 2022). "Taken together, our results indicate that CBX7 functions as a tumor suppressor to downregulate AKR1B10 and further inactivates ERK signaling." (PMID 34035231, 2021). "Depletion of AKR1B10 exerted the reduction of body weight in mice, and facilitated GC cells proliferation, which was manifested by the fact that tumor size and weight were greater than that of NC group." (PMID 34552036, 2021).